MAPK14 (mitogen-activated protein kinase 14)
Description:
Serine/threonine kinase which acts as an essential component of the MAP kinase signal transduction pathway. MAPK14 is one of the four p38 MAPKs which play an important role in the cascades of cellular responses evoked by extracellular stimuli such as pro-inflammatory cytokines or physical stress leading to direct activation of transcription factors. Accordingly, p38 MAPKs phosphorylate a broad range of proteins and it has been estimated that they may have approximately 200 to 300 substrates each. Some of the targets are downstream kinases which are activated through phosphorylation and further phosphorylate additional targets. RPS6KA5/MSK1 and RPS6KA4/MSK2 can directly phosphorylate and activate transcription factors such as CREB1, ATF1, the NF-kappa-B isoform RELA/NFKB3, STAT1 and STAT3, but can also phosphorylate histone H3 and the nucleosomal protein HMGN1. RPS6KA5/MSK1 and RPS6KA4/MSK2 play important roles in the rapid induction of immediate-early genes in response to stress or mitogenic stimuli, either by inducing chromatin remodeling or by recruiting the transcription machinery. On the other hand, two other kinase targets, MAPKAPK2/MK2 and MAPKAPK3/MK3, participate in the control of gene expression mostly at the post-transcriptional level, by phosphorylating ZFP36 (tristetraprolin) and ELAVL1, and by regulating EEF2K, which is important for the elongation of mRNA during translation. MKNK1/MNK1 and MKNK2/MNK2, two other kinases activated by p38 MAPKs, regulate protein synthesis by phosphorylating the initiation factor EIF4E2. In the cytoplasm, the p38 MAPK pathway is an important regulator of protein turnover. For example, CFLAR is an inhibitor of TNF-induced apoptosis whose proteasome-mediated degradation is regulated by p38 MAPK phosphorylation. In a similar way, MAPK14 phosphorylates the ubiquitin ligase SIAH2, regulating its activity towards EGLN3. MAPK14 may also inhibit the lysosomal degradation pathway of autophagy by interfering with the intracellular trafficking of the transmembrane protein ATG9. Another function of MAPK14 is to regulate the endocytosis of membrane receptors by different mechanisms that impinge on the small GTPase RAB5A. In addition, clathrin-mediated EGFR internalization induced by inflammatory cytokines and UV irradiation depends on MAPK14-mediated phosphorylation of EGFR itself as well as of RAB5A effectors. Ectodomain shedding of transmembrane proteins is regulated by p38 MAPKs as well. In response to inflammatory stimuli, p38 MAPKs phosphorylate the membrane-associated metalloprotease ADAM17. Such phosphorylation is required for ADAM17-mediated ectodomain shedding of TGF-alpha family ligands, which results in the activation of EGFR signaling and cell proliferation. Another p38 MAPK substrate is FGFR1. FGFR1 can be translocated from the extracellular space into the cytosol and nucleus of target cells, and regulates processes such as rRNA synthesis and cell growth. FGFR1 translocation requires p38 MAPK activation. In the nucleus, many transcription factors are phosphorylated and activated by p38 MAPKs in response to different stimuli. The p38 MAPKs are emerging as important modulators of gene expression by regulating chromatin modifiers and remodelers. The promoters of several genes involved in the inflammatory response, such as IL6, IL8 and IL12B, display a p38 MAPK-dependent enrichment of histone H3 phosphorylation on 'Ser-10' (H3S10ph) in LPS-stimulated myeloid cells. This phosphorylation enhances the accessibility of the cryptic NF-kappa-B-binding sites marking promoters for increased NF-kappa-B recruitment. Phosphorylates CDC25B and CDC25C which is required for binding to 14-3-3 proteins and leads to initiation of a G2 delay after ultraviolet radiation. Phosphorylates TIAR following DNA damage, releasing TIAR from GADD45A mRNA and preventing mRNA degradation. The p38 MAPKs may also have kinase-independent roles, which are thought to be due to the binding to targets in the absence of phosphorylation. Protein O-Glc-N-acylation catalyzed by the OGT is regulated by MAPK14, and, although OGT does not seem to be phosphorylated by MAPK14, their interaction increases upon MAPK14 activation induced by glucose deprivation. This interaction may regulate OGT activity by recruiting it to specific targets such as neurofilament H, stimulating its O-Glc-N-acylation. Required in mid-fetal development for the growth of embryo-derived blood vessels in the labyrinth layer of the placenta. Also plays an essential role in developmental and stress-induced erythropoiesis, through regulation of EPO gene expression. Isoform MXI2 activation is stimulated by mitogens and oxidative stress and only poorly phosphorylates ELK1 and ATF2. Isoform EXIP may play a role in the early onset of apoptosis. Phosphorylates S100A9 at 'Thr-113'. Phosphorylates NLRP1 downstream of MAP3K20/ZAK in response to UV-B irradiation and ribosome collisions, promoting activation of the NLRP1 inflammasome and pyroptosis. (Microbial infection) Activated by phosphorylation by M.tuberculosis EsxA in T-cells leading to inhibition of IFN-gamma production; phosphorylation is apparent within 15 minutes and is inhibited by kinase-specific inhibitors SB203580 and siRNA.
Synonyms: CSBP; SAPK2a; CSBP1; CSBP2; CSPB1; MXI2; p38alpha; PRKM14; p38; PRKM15; EXIP; RK
Tractability: Small molecule: a drug acting on it is in phase 2 or 3 trials; a structure with a bound ligand is known; a high-quality ligand is known; it has a high-quality binding pocket; it belongs to a druggable protein family. Antibody: its Gene Ontology location is reachable by antibodies, with high confidence. PROTAC: it is named in the literature on targeted protein degradation; UniProt records ubiquitination sites on it; ubiquitination databases record sites on it; its protein half-life has been measured; a small molecule that binds it is known.
Target class: Protein Kinase; CMGC protein kinase group; CMGC protein kinase p38 subfamily; CMGC protein kinase MAPK family; Enzyme; Kinase
Chemical probes: DORAMAPIMOD (high quality), FS-694 (high quality), Neflamapimod (high quality), PD004989, PD005362, PD007563, PD080785, PD080823, PD080871, PD080987, PD081041, PD081127, PD081199, PD081223, PD081235, PD081311, PD081366, PD081533, PD081548, PD081556, and 52 more
Gene: Protein-coding gene on chromosome 6 (36,027,738 to 36,122,511, forward strand). Ensembl gene ENSG00000112062.
Subcellular location: Cytoplasm; Nucleus
Subcellular location (Human Protein Atlas): Nuclear speckles; Cytosol
Pathways (Reactome):
Immune System: Activation of the AP-1 family of transcription factors; NOD1/2 Signaling Pathway; Neutrophil degranulation; activated TAK1 mediates p38 MAPK activation
Signal Transduction: ERK/MAPK targets; RHO GTPases Activate NADPH Oxidases; VEGFA-VEGFR2 Pathway; p38MAPK events
Developmental Biology: Myogenesis; Regulation of MITF-M-dependent genes involved in pigmentation
Hemostasis: ADP signalling through P2Y purinoceptor 1; Platelet sensitization by LDL
Cell Cycle: Ubiquitin-Mediated Degradation of Phosphorylated Cdc25A
Cellular responses to stimuli: Oxidative Stress Induced Senescence
Disease: CD163 mediating an anti-inflammatory response
Metabolism of RNA: KSRP (KHSRP) binds and destabilizes mRNA
Organelle biogenesis and maintenance: Activation of PPARGC1A (PGC-1alpha) by phosphorylation
Gene Ontology:
Molecular function: enzyme binding; MAP kinase activity; mitogen-activated protein kinase p38 binding; protein binding; protein phosphatase binding; protein serine kinase activity; protein serine/threonine kinase activity; MAP kinase kinase activity; NFAT protein binding; ATP binding; protein kinase activity
Biological process: cellular response to ionizing radiation; cellular response to lipopolysaccharide; cellular response to lipoteichoic acid; cellular response to UV-B; cellular response to vascular endothelial growth factor stimulus; cellular response to virus; intracellular signal transduction; negative regulation of hippo signaling; p38MAPK cascade; positive regulation of blood vessel endothelial cell migration; positive regulation of cyclase activity; positive regulation of erythrocyte differentiation; positive regulation of gene expression; positive regulation of interleukin-12 production; positive regulation of reactive oxygen species metabolic process; regulation of cytokine production involved in inflammatory response; signal transduction in response to DNA damage; stress-activated MAPK cascade; stress-activated protein kinase signaling cascade; stress-induced premature senescence; vascular endothelial growth factor receptor signaling pathway; 3'-UTR-mediated mRNA stabilization; cell surface receptor signaling pathway; cellular senescence; chemotaxis; and 10 more
Cellular component: cytoplasm; cytosol; nuclear speck; nucleus; extracellular region; ficolin-1-rich granule lumen; nucleoplasm; secretory granule lumen
Genetic constraint (gnomAD): Loss-of-function variants: 8 observed, 25.59 expected, observed/expected ratio (o/e) 0.31, 90% interval 0.18 to 0.56. The upper end of that interval is the gene's LOEUF score, 0.56, which puts it in group 2 of 6, group 1 being the genes least tolerant of losing a copy. Missense variants: 137 observed, 268.77 expected, observed/expected ratio (o/e) 0.51, 90% interval 0.44 to 0.59. Synonymous variants: 91 observed, 98.43 expected, observed/expected ratio (o/e) 0.92, 90% interval 0.78 to 1.1.
Homologues: Orthologues: chimpanzee MAPK14 (100% identical), macaque MAPK14 (99% identical), guinea pig MAPK14 (99% identical), rat Mapk14 (99% identical), dog MAPK14 (95% identical), mouse Mapk14 (95% identical), pig MAPK14 (95% identical), tropical clawed frog mapk14 (86% identical), zebrafish mapk14b (72% identical), zebrafish mapk14a (72% identical), Caenorhabditis elegans pmk-1 (64% identical), Drosophila melanogaster p38b (61% identical), and 5 more. Paralogues in human: MAPK11 (74% identical), MAPK12 (62% identical), MAPK13 (60% identical), MAPK9 (52% identical), MAPK10 (50% identical), MAPK8 (50% identical), MAPK1 (45% identical), MAPK3 (45% identical), MAPK7 (45% identical), NLK (39% identical), MAPK15 (36% identical), MAPK6 (35% identical), and 7 more.
Diseases named in the same sentence as MAPK14 in open-access papers:
MAPK14 is named in the same sentence as 286 diseases in open-access papers, as found by Europe PMC text mining. Sharing a sentence is not in itself a finding about the gene and the disease. The quoted sentences say what the papers report.
breast cancer (62 papers, 2007 to 2026). A primary or metastatic malignant neoplasm involving the breast. "It was reported that phosphorylated MAPKs including ERK2 (MAPK1), JNK1 (MAPK8) and p38 MAPK (MAPK14) over-expressed in breast cancer patients and is associated with poor prognosis." (PMID 33246450, 2020). "p38 (encoded by the MAPK14 gene) is amplified or overexpressed in 9.5% of the Black/African American breast cancer patients." (PMID 32873298, 2020). "In the present project, we evaluated expression of MAPK14 and four associated lncRNAs in breast cancer tissues and ANCTs." (PMID 32433496, 2020). "Module 2 includes genes whose abnormal function has been directly associated with breast cancer, such as MAPK14, BRCA1, CDH1, HIF1A, CDKN2A and other members/regulators of the CDK family." (PMID 29093438, 2017). "This study employed phosphoproteomic analysis to investigate ARID1A phosphorylation in breast cancer, identifying predominant phosphosites-S363, S1184, and S696-regulated by kinases such as MAPK14, CDK16, and MAPK9." (PMID 41572083, 2026). "MAPK14 serves dual essential functions in mammary carcinoma cells by ensuring genomic integrity and orchestrating DNA repair mechanisms." (PMID 40070022, 2025). "There is a similar survival probability between breast cancer patients with low and with high MAPK14 expression, and interestingly, MAPK14 phospho-T180/Y182 seems to have a protective effect." (PMID 35501462, 2022). "More importantly, BCa mouse models, demonstrated the critical role of p38α (Mapk14) during the initiation, and proliferation of mammary tumors." (PMID 33707576, 2021). "In brief, in the present study, we introduced an in silico method for identification of MAPK14-related lncRNAs with putative ceRNA role in breast cancer and assessed expression of these lncRNAs in breast cancer tissues and ANCTs." (PMID 32433496, 2020). "We confirmed that 8 genes—MAPK14, CLOCK, NF2, HMGA2, CXCL12, E2F1, NOTCH1, and CD24—are associated with breast cancer." (PMID 30013305, 2018). "Our research re-evaluates the carcinogenic risks of plastic stabilizers and suggests that PSs may enhance breast cancer progression via targets such as MAPK14, PIM1, and TRDMT1." (PMID 41790613, 2026). "THSWD treatment of breast cancer may be related to targeting Ras, FoxO, PI3K-Akt, and other signal pathways associated with the core targets HRAS, MAPK1, AKT1, GRB2, and MAPK14." (PMID 34513708, 2021). "THSWD could regulated the RNA and protein expression of core targets HRAS, MAPK1, AKT1, GRB2, and MAPK14 for treatment of breast cancer." (PMID 34513708, 2021). "Finally, we found that within MAPK14, preferential retention of intron 2 occurred specifically in 4T07-derived mammary tumors." (PMID 20700505, 2010). "However, some evidences point to a tumor suppressive role of MAPK14 in breast cancer." (PMID 32433496, 2020). "Notably, considering the wide expression and tumorigenic function of MAPK14 across a wide variety of cancers, including breast cancer, lung cancer, and colon cancer among others, it suggests that lobeline could potentially target MAPK14 in multiple malignancies beyond CRC." (PMID 39840525, 2025). "Our study has made groundbreaking progress in identifying key transcription factors, such as SP1, E2F1, and SIN3A, as well as kinases, including MAPK14, CSNK2A1, and CDC2, whose role in breast cancer progression is paramount." (PMID 38084295, 2023). "LncRNA LIPE-AS1 was co-expressed with 5 ferroptosis-related genes (HRAS, PHKG2, MAPK14, EGLN2, and GPX4), including 4 ferroptosis driver and 1 ferroptosis suppressor, and we found that LIPE-AS1 was a protective factor for breast cancer patients’ prognosis." (PMID 34164433, 2021).
breast cancer (continued). "For instance, response to cisplatin can be enhanced by MAPK14 inhibition, resulting in ROS‐dependent upregulation of the JNK pathway in colon and breast cancer cells." (PMID 33021050, 2020). "For breast cancer, of the six predicted candidates (PRKCQ, ARAF, MAPK14, BRMS1, CDC42BPA, SP3), three (PRKCQ, ARAF, MAPK14) are members of at least one KEGG cancer relevant pathway." (PMID 25961669, 2015). "Notably, MAPK14 has an essential role in induction of cell migration and epithelial-to-mesenchymal transition (EMT) in breast cancer cells through cooperation with TGF-β13." (PMID 32433496, 2020). "This can be explainedby suppression of MAPK1 and MAPK14 to some extent.Therefore, suppression of TGF-β mediators may providea good reason behind the partial cell cycle arrest observedin the breast cancers, following overexpression of miR302/367 cluster." (PMID 31376326, 2020). "Finally, we assessed expression of MAPK14-related lncRNAs in breast cancer samples and adjacent non-cancerous tissues (ANCTs)." (PMID 32433496, 2020). "Expression levels of MAPK14 and NORAD were not significantly different between breast cancer tissues and ANCTs." (PMID 32433496, 2020). "However, expression levels of MAPK14 and NORAD were not significantly different between breast cancer tissues and ANCTs." (PMID 32433496, 2020).